IL10 (interleukin 10)
Diseases named in the same sentence as IL10 in open-access papers (continued):
Sharing a sentence is not in itself a finding about the gene and the disease.
tumor (continued). "M2-Mφs suppress tumor immunity and accelerate tumor progression by secreting immune suppressive factors, such as cytokines (TGF-β and IL-10) and chemokines (CCL2, CCL17, CCL22, and CCL24)." (PMID 35155237, 2022). "Tumor cells, including CCA, recruit protumorigenic immune cells by secreting a variety of immunosuppressive substances such as TGF-β and IL10, which can attract Tregs." (PMID 35392957, 2022). "Evidence shows that TAMs secret multiple immunosuppressive mediators, such as transforming growth factor (TGF)-B1 and interleukin-10 (IL-10), CCL2-CCR2 pathways, play a crucial role in hindering immunotherapy efficiency tumor and promoting tumor progression." (PMID 35651805, 2022). "In this study, we observed that miR‐192‐5p affects tumour EMT by regulating RB1, inducing the secretion of IL‐10 to promote FOXP3+Treg cell differentiation and PD‐1 expression on Tregs in the TME." (PMID 35969010, 2022). "This view relates to the CAF secretome containing factors such as IL-10, TGFβ, IFNγ and IL-6 that are known to recruit macrophages, natural killer cells and CD3+ T lymphocytes during tumor initiation to promote an anti-tumor immune response." (PMID 36671452, 2022). "Collectively, our studies indicate that miR‐192‐5p/RB1 promotes EMT of tumour cells, and the miR‐192‐5p/RB1/NF‐κBp65 signaling axis induces Treg cell differentiation by regulating IL‐10 secretion in GC." (PMID 35969010, 2022). "Using paracrine signaling from VEGFA, IL-10, and PGE2, this tumor endothelial death barrier is established, and inhibition of VEGFA and PGE2 inhibits FasL expression leading to tumor attenuation mediated by cytotoxic T cells." (PMID 36140392, 2022). "This system is a vicious circle because TAMs are promoted by the tumor itself, which secretes various factors such as IL-6, IL-10, TGF-β, and PGE2, and in return, TAMs promote the tumor’s proliferation and survival." (PMID 35214076, 2022). "In the present study, we also investigated the expression profile of tumor immunoregulatory genes TNF-α, TGF-β, IL-10, and iNOS in macrophages conditioned with OSCC tumoral media treated with PL during polarization." (PMID 36686704, 2022). "Several tumor-suppressive factors containing cytokines like TGF-β and IL-10 have been discovered in LGG." (PMID 35310911, 2022). "Tregs cultured in conditioned medium from OCSCs exhibited increased IL-10 and MMP-9 expression which enhanced the tumor invasion." (PMID 35269636, 2022). "They involve STAT3-inducing cytokines (IL-10, IL-6 and LIF), TGFB1 mainly expressed by TAMs, WNT7A mainly expressed by tumor cells, multiple S100 genes, semaphorins and their receptors (plexins and neuropilins), ephrins, chemokines and their receptors." (PMID 35682890, 2022). "CAFs also produce CCL2, CXCL12, IL-6, IL-10, glycoprotein CHI3L1, macrophage colony-stimulating factor to promote the migration of monocytes into tumor tissue and support their transdifferentiation into the M2 phenotype." (PMID 36324128, 2022). "More importantly, FOLR2+ TAMs significantly expressed typical immunosuppressive genes including TGFB1, TGBR1, IL10, and IL10RB, validating the immunosuppressive role of FOLR2+ TAMs in the HCC tumor niche." (PMID 36238304, 2022). "Furthermore, a large body of evidence associates the activation of the IFN pathway and tumor development, whilst lower levels of IL10 cytokine were detected in the sera of HCV-HCC, suggesting that further studies are required to assess whether IL10 supports anti-tumor immunity." (PMID 35267563, 2022). "Overall, NEO increased the proinflammatory function of tumor-infiltrating CD4+ T cells, with enhanced TNF-α and IL-2 but reduced IL-4 and IL-10 expression." (PMID 36509285, 2022). "CAF-educated myeloid cells are transformed into pro-tumor macrophages, leading to the suppression of T cell proliferation by upregulating TGFB1 expression and IL10 production." (PMID 35455650, 2022).
tumor (continued). "NK cells participate in autoimmunity by secreting IL-1, IL-5, IL-8, IL-10, tumor necrosis factor-α (TNF-α), and Interferon-γ (IFN-γ) to kill aging, virus-infected, and tumor cells." (PMID 36428567, 2022). "This exhaustion state is marked by inhibitory cell surface receptors (PD1, CTLA-4, LAG-3, TIM3, and others), in addition to anti-inflammatory cytokines such as IL-10 and TGF-ß present in the tumor microenvironment." (PMID 35177622, 2022). "By contrast, TAMs can secrete soluble factors including growth factors, cytokines, and chemokines such as transforming growth factor [TGF]-β, vascular endothelial growth factor, M-CSF, IL-10, and CXCL10 to induce tumor progression and metastasis." (PMID 35960749, 2022). "Autophagosomes-induced CD4+ T cells in an IL-6- and IL-10-dependent manner suppress CD4+ and CD8+ effector T cell functions and induce IL-10-producing Breg cells via IL-6, IL-10 and IL-21, thereby promoting tumor growth and metastasis." (PMID 36365103, 2022). "During tumour EMT, tumour cells secret cytokines including TGF‐β and interleukin‐10 (IL‐10) to induce T cells into Tregs, thereby promoting tumour progression and metastasis." (PMID 35969010, 2022). "Upon addition of a tumor-conditioned medium (TCM) to an anti-tumor cytokine cocktail (IL-4 and IL-10) in addition to M-CSF, TAMs can be generated." (PMID 36358879, 2022). "The mechanisms mainly involve the downregulation of MHC molecules, tumor antigens or the secretion of cytokines such as TGF-β and IL-10." (PMID 36313280, 2022). "It has been revealed that in the microenvironment of HNSCC, increased expressions of IL-4, IL-10 and transforming growth factor β (TGF-β) suppress adaptive immunity and promote tumor escape from immune system." (PMID 36376825, 2022). "IL-10 stimulates TAMs to activate STAT3 signaling, which promotes the release of VEGF-A and supports tumor angiogenesis." (PMID 36510315, 2022). "Interleukin-10-Fc (IL-10/Fc) fusion protein has been identified to mediate proliferation and effector function of terminally exhausted CD8+ tumor infiltrating leukocytes via metabolic shift towards OXPHOS through the mitochondrial pyruvate carrier." (PMID 36147929, 2022). "Cytokines, chemokines and metabolites from tumor cells have a significant impact on TIME, such as transforming growth factor-β (TGF-β) and interleukin (IL)-10." (PMID 36532071, 2022). "STAT3 signaling in Tregs can upregulate the expression of TGF-β and IL-10, which conversely restrain IFN-γ production by CD8+ T cells, and finally inhibit the tumor-killing activity of CD8+ T cells." (PMID 34875483, 2022). "BC-MSCs and GC-MSCs induce generation of Tregs and their production of IL-10, IL-17 and TGF-β, in turn, facilitating tumor cell progression." (PMID 35842634, 2022). "Tumor cells release transforming growth factor-beta 1 (TGF-β1), IL-4, IL-6, and IL-10 that educate TAM to polarize into M2 or become immunosuppressive." (PMID 36555392, 2022). "To this end, we measured the cytokines IL-1, IL-10, and TNF-α produced by these tumor-conditioned macrophages." (PMID 36686704, 2022). "While IL-10 and TGF-β are important in lung homeostasis, they are a decidedly pro-tumor component in the context of the TME." (PMID 35406557, 2022). "Elevated neutrophils can secrete interleukin (IL)-1, IL-10, and vascular endothelial growth factor (VEGF), thereby inhibiting lymphocytes and natural killer cells, stimulating angiogenesis and promoting tumor progression." (PMID 36387142, 2022). "M2 macrophages support tumor growth by secreting vascular endothelial growth factor (VEGF), transforming growth factor-β (TGFβ), IL10, and also through expression of PD-L1." (PMID 36421358, 2022). "Accordingly, some groups have shown experimentally that NKEVs retain tumor affinity, tumor suppressive, and immunomodulatory properties in simulated immunosuppressive TMEs using TGF-β, IL-10, and LPS." (PMID 35874677, 2022).
tumor (continued). "PD-1+ Bregs operate via IL-10-dependent pathways to induce CD8+ T cell dysfunction and thereby create conditions that are conducive to tumor progression." (PMID 36618354, 2022). "TAMs are known to contribute to tumor growth, infiltration, and neovascularization via multiple mechanisms, such as secretion of cytokines and growth factors—TGF-β, IL10, IL6, IL1β, pleiotrophin, and EGF." (PMID 35920986, 2022). "It has been reported that the elevated local concentrations of various stromal‐derived factors such as IL‐10 and TGF‐β serves critical roles in tumour‐mediated disruption of normal NK cell function." (PMID 35762299, 2022). "Tregs then secret IL-10, TGF-β, and IL-35 to downregulate antitumor immunity, suppress the antigen presentation by DCs, and decrease the tumor-specific CTLs." (PMID 36613591, 2022). "We evaluated the ex vivo number of IL-2-, IL-6-, IL-10-, IL-12-, TNF-α- and IFN-γ-producing spleen cells, since tumor growth can be affected by cytokines." (PMID 35265317, 2022). "To determine the effects of IFN-γ/St.∆ppGpp on tumor inflammatory cytokines, we removed the tumor tissue from CT26 tumor-bearing mice and used qRT-PCR to measure Il-1β, Tnf-α, Tgf-β, Il-6, Il-10, Gm-CSF, and G-CSF." (PMID 36246355, 2022). "Instead of clustering with cytotoxic T cells, tumor cells in A-CIA cluster with macrophages (CD68) and B cells (CD20), both of which can produce IL-10 (also found in the A-CIA tumor cluster)." (PMID 35379804, 2022). "M-CSF promotes the development of monocytic MDSCs (M-MDSCs) that mainly utilize nitric oxide (derived from iNOS), IL-10, TGF-β, and PD-L1 to suppress anti-tumor immune responses." (PMID 36248881, 2022). "Tumor-infiltrating pDCs are also able to recruit other suppressive cells in the tumor microenvironment such as myeloid suppressive cells, IL10+CCR7+CD8+Foxp3+ induced Tregs, and IL-10+ IL-17+ Foxp3neg type-1 regulatory T cells (Tr1)." (PMID 35884612, 2022). "Cytokines such as IL-6, IL-10, and TGF-β produced by tumor cells in the TME hinder the activation of NK cells." (PMID 36686745, 2022). "Treg cells are a subset of CD4+ T cells that suppress innate and adaptive immune responses mainly by secreting IL-10 and TGF-β, which are known to promote tumor progression by inhibiting antitumor immune response." (PMID 35433771, 2022). "M2 TAMs secrete pro-tumor factors (such as IL-4, IL-6, IL-10, IL-13, EGF, and VEGF), while the tumor suppressor M1 TAMs expresses anti-tumor factors (such as IL-12, the major histocompatibility complex (MHC) class II, and TNF-α)." (PMID 36358823, 2022). "These cells contribute to immune tolerance by secretion of IL-10 but also other inhibitory molecules, including PD-L1, granzyme B, TGF-β, and IL-35, leading to the induction of tumor immunosuppressive cells." (PMID 35055124, 2022). "M2 macrophages secrete many factors, such as, IL-6, IL-8, IL-10, TGF-β, PGE2 and MMP7, and these macrophages promote immunosuppression and tumor growth." (PMID 36059695, 2022). "It was also shown that IL-10, VEGF and prostaglandin E2 (PGE2) enhance the expression of FasL in tumour cells." (PMID 36011012, 2022). "This incapacity was correlated to a low concentration of HGMB1 and Hsp60 and a high concentration of IL-10 and TGF-β present in LMM3-tumor lysate." (PMID 35922755, 2022). "The tumor size and weight, gene expression (IL10, INF-γ, TGFβ, and FOXP3), and pathological properties of the tumor and normal tissues were assessed." (PMID 36544523, 2022). "Interleukin (IL)-10, as a major immunosuppressive cytokine in TME secreted by tumor cells, can help tumor cells escape immunological recognition and destruction." (PMID 35784354, 2022). "Concerning moDCs, they can loss its anti-tumour activity and may contribute to an immunosuppressive environment at the tumour site in lung and CRC patients and in human SCC microenvironment wherein TGF-β, IL-10 and VEGF-A can suppress DC function resulting in impairment of T cell activation." (PMID 35406451, 2022).
tumor (continued). "TGF-β and IL-10 promote the differentiation of iTregs by up-regulating the expression of Foxp3 and CTLA-4, leading to the proliferation and migration of tumor cells, resulting in poor prognosis of patients." (PMID 35541908, 2022). "Tregs can inhibit the function of tumor-specific T cells by secreting the inhibitory factors IL-10 and TGF-β and activating the CTLA-4 pathway to promote tumor immune escape." (PMID 36358736, 2022). "This has been observed in murine colorectal cancer (CRC) tumor models, where IL-22 producing ILC3 trans-differentiated into IL-10 producing regulatory ILCs (ILCregs), thereby promoting CRC." (PMID 36189323, 2022). "M2 macrophages mainly secrete cytokines such as IL-10 and TGF-β to inhibit inflammation as well as T cell proliferation and differentiation and promote tumor cell proliferation and tumor matrix angiogenesis." (PMID 36304995, 2022). "M2d macrophages, also known as tumor-associated macrophages (TAMs), are induced by the TLR antagonists, and they release IL-10, TGF-βand vascular endothelial growth factors (VEGF) to contribute to tumor angiogenesis." (PMID 36119080, 2022). "It was also found that IL-10-producing Bregs limit anti-tumor immunity via TNF-α and promote tumor development by attenuation of CD8+INF-ƴ+ T cells responses." (PMID 36618354, 2022). "This emphasised the key association of D14 neutrophils, PD-L1+ myeloid cells and Ly6Cintermediate monocytes with CT26 tumour size, and a more distant relationship with D7 myeloid cells, CCL17, CXCL1, CCL2, CXCL10 levels, and D14 IL-10 level." (PMID 35226704, 2022). "As a receptor for IL10, IL10RA can regulate tumor immune responses and is highly expressed in HNSCC tissues." (PMID 35480305, 2022). "In vivo studies showed that triptolide was able to decrease TGF‐ β, IL10 and VEGF in B16‐F10 xenograft mouse tumour model." (PMID 35384373, 2022). "Second, the group of cytokines were triggered in response to the resection procedure and then sustained in the newly regrown tumor (IL4, IL5, IL10, IL17, CCL2, IFN-γ and GM-CSF)." (PMID 35884700, 2022). "In both prophylactical and therapeutic settings, therapeutic vaccination with the simultaneous blocking of interleukin 10 (IL-10) increased antigen-specific CD8+ T cell responses, which consequently improved tumour growth inhibition." (PMID 36497272, 2022). "The expression of VISTA on CD4+ T cells in tumor tissue showed low secretion of cytokines including IFN-γ, IL-2, IL-4, IL-10, IL-17, and IL-12p70." (PMID 35122478, 2022). "During tumor progression, these changes depend on various conditions, such as hypoxia, production of PGE2, IL-10, adenosine, and lactate level increase." (PMID 36419156, 2022). "MDSCs express IL-10 in a TNFR2-dependent way, facilitating the activation of B cells and the production of IgA, thereby promoting tumor development." (PMID 36358977, 2022). "In HNSCC, tumor cell-derived Sema4D inducing MDSC polarization corresponded with an inhibition in T-cell activation and an increase in arginase-1, TGF-β, and IL-10 production." (PMID 35155237, 2022). "The activity of JAK and STAT3 is enhanced due to the overexpression of pro-inflammatory cytokines like IL-6, IL-10, IL-11, and TGF-α to regulate the tumor micro-environment, which eventually create the oncogenic conditions to inhibit apoptosis." (PMID 35401182, 2022). "IL-10 and TGF-β1 inhibit T-lymphocyte function in the TME and have been considered key immunosuppressive factors released by TAMs, MDSCs, and tumor cells." (PMID 35878391, 2022). "In tumour-bearing mice, MDSCs induce the emergence of a population of splenic PD1-PD-L1+CD19+IL-10-secreting B cells that inhibit effector T cell proliferation and IFNγ expression." (PMID 35350071, 2022). "The gene expression of IL-10, TGFb1, S100A8, S100A9, and IL10RA was increased in TAMs compared to tumor cells isolated from ascites of OC patients." (PMID 35682890, 2022).
tumor (continued). "The proliferation of CD4+CD25+ Treg cells can be stimulated by inhibitory cytokines, such as IL-10 and TGF-β secreted from tumor cells within the TME, and they directly inhibit the activation of CD8+ effector T cells and restrict their IL-2 production." (PMID 36553542, 2022). "The effects of yeast and Lactobacillus for either treatment or vaccination (3 times/week) on the tissue and serum levels of TGF-β, IL-4, IL-10, and IFN-γ were measured on day 35 of tumor cell transplantation." (PMID 35974992, 2022). "Tregs, the important Tumor-Promoting Immune Cells, affect a variety of tumor-infiltrating immune cells by producing multiple immunosuppressive cytokines (such as TGF-β, IL-10 and IL-35) and exhibit a significant anti-tumor immune response." (PMID 36532071, 2022). "When the TME becomes more pro-tumor, IL4, IL13, or IL10, produced by Th2 or Treg cells, promote M2 or M2-like phenotype for TAM, displaying protumor functions." (PMID 35163420, 2022). "From healthy tissues to tumor tissues (PTX-sensitive) and subsequently to tumor tissues (PTX-resistant), the expression of IL-10 was elevated." (PMID 35127342, 2022). "The expression of other M2 marker genes, including Arg‐1, IL‐10, CCL8, Fizz1 and YM‐1, were also upregulated in the tumor from Senp3 cKO mice, as demonstrated by qRT‐PCR analysis." (PMID 33932085, 2022). "CAM-type macrophages express MHC II, CD86, NO, iNOS, showing the characteristics of pro-inflammatory response and anti-tumor, while AAM-type macrophages express IL-10, arg-1, CD206, CD163, TGF-β, showing immunosuppressive and tumor-promoting characteristics." (PMID 36439090, 2022). "TAMs can secrete cytokines and chemokines such as C-C chemokine ligand (CCL) 3, CCL4, TGFβ, and IL10, which recruit regulatory T cells (Tregs) to the TME and suppress the function of CD4+ and CD8+ T cells, thereby promoting tumour progression." (PMID 36497148, 2022). "In tumor animal models, resistance training can increase the IL-10/TNF-α ratio and plasma IL-10 levels, exerting an anti-inflammatory effect." (PMID 35805170, 2022). "Among these 9 candidate targets, AGT, DRD2, IL-1B, and IL-6 were significantly increased in primary tumor compared with the normal tissues, while ALB, IL-10, and IGF1 were significantly decreased in COAD tissues." (PMID 35280511, 2022). "M2 macrophages produce several anti-inflammatory cytokines, such as IL-4, IL-10, IL-13, vascular endothelial growth factor (VEGF), and TGF-β, to inhibit immune systems and promote tumor progression." (PMID 36613591, 2022). "Much like M2 macrophages, MDSCs produce STAT3 transcriptional targets, including IL-10, TGF-β, VEGF, arginase-1, and IDO, to generate an immunosuppressed, pro-tumor TME." (PMID 35406557, 2022). "Inhibition of IL-10 signaling at the time of immunization promotes the generation of robust vaccine-induced CD8 T responses, which are able to inhibit tumor growth." (PMID 33628584, 2021). "TAMs modulate the CCA microenvironment by secreting TNFα, TGFβ (tumor growth factor-β), IL6, IL10, and VEGF-A (vascular endothelial growth factor-A), which support epithelial-to-mesenchymal transition (EMT), tumor growth, and metastasis." (PMID 33579265, 2021). "In mouse B-cell melanoma, granulocytic MDSC (G-MDSC) and monocytic MDSC (M-MDSC) highly express miR-30a, which can further upregulate ARG1, IL-10, and ROS to promote the differentiation of MDSC and increase tumor growth." (PMID 34084160, 2021). "Conversely, the M2 macrophages play an important role in cancer promotion, tumor growth, angiogenesis, and metastasis, through the secretion of cytokines including IL4, IL-10, and transforming growth factor (TGF)-β." (PMID 34867821, 2021). "Previous studies have shown that the anti-inflammatory IL10 was overexpressed in both intratumoral and peritumoral hepatic tissues of HCC patients, and has delivered multiple tumor-promoting functions in both areas of the liver." (PMID 33633112, 2021).